TNF (tumor necrosis factor)
Diseases named in the same sentence as TNF in open-access papers (continued):
Sharing a sentence is not in itself a finding about the gene and the disease.
latent infection (continued). "Host responses in controlling the latent infection may include macrophage activation, maintenance of granuloma structure, and expression of IFN-γ, TNF-α, CD4 T cells, and CD8 T cells." (PMID 31992621, 2020). "This variability is reflected in the experimental J-Lat cell line models for latent infection, where clones containing distinct integration sites for the HIV-1 provirus respond with different levels of virus reactivation to the same stimulant, such as PMA or TNF-α." (PMID 36672628, 2023). "Importantly, the results demonstrate that immunosuppression by anti-TNF-alpha treatment does not lead to activation of a possible latent infection and appearance of joint swelling in the antibiotic treated mice." (PMID 25816291, 2015). "Several HIV activating agents, including Tumor Necrosis Factor alpha (TNFα) and other agents that activate via NF-kB are not fully effective in all latent infection models due to epigenetic restrictions, such as DNA methylation and the state of histone acetylation." (PMID 20942961, 2010). "Indeed, we found that combined analysis of TNF-α, IL-12(p40) and IL-17 production following stimulation with TB10.4 for 7 days resulted in 85% correct classification into subjects with active disease or those with latent infection." (PMID 20811496, 2010).
ZIKV infection (79 papers, 2016 to 2026). "ZIKV activation of CD8 T cells has been associated with significant IFN gamma, TNF alpha, and granzyme B production (88, –, 90), all of which are cytotoxic, despite being required to control ZIKV infection." (PMID 40401980, 2025). "ZIKV infection has also been associated with enhanced microgliosis and elevated pro-inflammatory cytokine production, including TNF-α." (PMID 40654990, 2025). "Taken together, these results demonstrated that ZIKV infection causes pyroptosis of JEG-3 cells via the TNF-α-caspase-8-caspase-3-GSDME signaling pathway." (PMID 35972780, 2022). "PTGS2 and TNF have both been implicated as being overexpressed during ZIKV infection, with TNF overexpression being directly associated with severe microcephaly." (PMID 35746681, 2022). "Further, a previous study with a similar approach testing candidate SNPs demonstrated Toll-like receptor 3 (TLR3) rs3775291 and Tumor Necrosis Factor (TNF) rs1799964 associated with abnormal outcomes due to ZIKV infection during pregnancy." (PMID 34899713, 2021). "ZIKV infection was associated with concomitant secretion of inflammatory mediators linked with central nervous system inflammation such as IL-6, TNF-α, IL-1β, iNOS and NO." (PMID 30359409, 2018). "Collectively, our data demonstrate that the TNF-α signaling pathway plays an important role in ZIKV-induced placental damage and CZS, which highlights TNF-α as a potential therapeutic target for abnormal pregnancy and adverse fetal outcomes caused by ZIKV infection." (PMID 35972780, 2022). "Hence, we examined the ISGs transcript levels for DDX58, IFIT1, ISG15, and IFNB1, and analyzed the transcript levels of inflammatory cytokines including TNF-α and IL-6 that are associated with severe symptoms during ZIKV infection." (PMID 34745057, 2021). "In the same study, ZIKV infection was associated with concomitant secretion of inflammatory mediators linked to CNS inflammation and alterations in endothelial and microvascular permeability, such as IL-6, TNF-α, IL-1β, iNOS, and NO." (PMID 31620112, 2019). "MEL treatment reduced viral brain loads by 3–4 log units and modulated neuroinflammatory markers, notably reducing IL-1β, TNFα, and NF-κB during ZIKV infection, and modulating TNFα, IL-1β, and NF-κB during DENV-4 infection." (PMID 40821819, 2025). "Our studies show elevated IL1β and TNFα gene expression up to day 7, likely driven by ZIKV infection and apoptosis in brain tissue." (PMID 40688087, 2025). "We found that during acute infection, ZIKV infection induces robust expression of inflammatory genes, such as IL-6, TNFα, and IL-1β in the brain." (PMID 40688087, 2025). "Morphological assessments showed decreased cell death in iBMDMs stimulated with LPS plus Ni or TNF plus CHX after ZIKV infection." (PMID 39976465, 2025). "Expression analysis of neuroinflammatory markers revealed that melatonin reduced IL-1β, TNFα, and NF-κB during ZIKV infection." (PMID 40821819, 2025). "Complementing our analysis with a 49-plex ELISA, we demonstrate that ZIKV infection induces a clinically relevant and diverse pro-inflammatory brain tumour cell secretome, including TNF-alpha." (PMID 40240536, 2025). "During the acute phase of ZIKV infection, patients have elevated serum levels of pro- and anti-inflammatory cytokines, including tumor necrosis factor alpha (TNFα), interleukin (IL) 1β (IL1β), IL2, IL4, IL6, IL9, IL10, IL13, and IL17." (PMID 38839691, 2024). "Inflammatory cytokines (e.g., IL-1β, IL-6, and TNF-α) induced following Zika virus infections in human macrophages also upregulate CH25H in type I IFNs in an independent manner." (PMID 37631994, 2023). "ZIKV infection induced the expression of proinflammatory cytokines, including interleukin-1β (IL-1β), IL-6, gamma interferon, and tumor necrosis factor alpha, in the brains of Ifnar1−/− mice." (PMID 37191498, 2023).
ZIKV infection (continued). "TNF-a presents the potential to cause neural tube defects, IFN-g is related to impaired placental development following Zika virus infection, and IL-1b can induce preterm labor." (PMID 37376620, 2023). "TNF-α stimulation further increased ZIKV infection, and si-circ_0007321 or miR-492 mimic treatment induced NF-κB relative luciferase activity in 293T cells." (PMID 38051045, 2023). "Together, these data confirm that TNF-α signaling is active in both cultured neurons and the brain in vivo following ZIKV infection." (PMID 35462541, 2022). "Consistent with the in vitro result, ZIKV infection also significantly increased the production of TNF-α in mouse placenta." (PMID 35972780, 2022). "In contrast, TNF-α treatment induced a strikingly similar pattern of differential expression to that induced by ZIKV infection." (PMID 35462541, 2022). "Taken together, these data suggest that the induction of TNF-α following neuronal ZIKV infection is a major regulatory mechanism that alters expression of genes relevant to neuronal function." (PMID 35462541, 2022). "Grifoni and colleagues elucidated in-depth characterization of human CD8+ T cells responding to ZIKV infection that are characterized by a polyfunctional IFNγ signature with upregulation of TNFα and related activation markers." (PMID 35793354, 2022). "ADE of ZIKV infection in HBCs significantly induced production of TNF-α and IP-10 compared to uninfected HBCs (1.7-fold increase and 4.1-fold-increase respectively, P = .014 and P = .0001)." (PMID 35442976, 2022). "ZIKV infection promoted muscle lesions, with infiltration of inflammatory cells, along with an upregulation of proinflammatory cytokines (TNF, IL-1β, and IL-6) and chemokines (RANTES and MCP-1) involved in monocyte/macrophage recruitment (39, –, 41)." (PMID 34468171, 2021). "TRAIL/APO2L levels were unaltered at 1 dpi and FasL/CD95L, TWEAK/ APO3L, and TNF-α levels remained unaltered throughout the first 48 h of ZIKV infection." (PMID 34834918, 2021). "In general, ZIKV infection elicited rapid increase in serum cytokines and chemokines (specifically IFNγ, TNFα, MCP-1, IL-15, IL-10, IL1RA, MIP-1β), with responses peaking around 1–2 days post-infection." (PMID 34120576, 2021). "Our findings showed higher risk of CZS due ZIKV infection in the first trimester and suggested that polymorphisms in NOS2 and TNF genes affect the risk of CZS and severe microcephaly." (PMID 33672623, 2021). "Children with 2SD of microcephaly were compared to children with 3SD of microcephaly for the frequency of two variables already reported in the literature as related to these phenotypes—trimester of ZIKV infection and TNF gene." (PMID 33672623, 2021). "Microglia and activated astrocytes produce several inflammatory mediators, including IL-1β, TNF, glutamate, nitric oxide (NO) among others, which can trigger neuronal death after ZIKV infection." (PMID 34335614, 2021). "Neutralization of TNF-α or depletion of microglia prevents memory impairment in ZIKV-infected mice, indicating that microglia and TNF-α play detrimental roles in ZIKV infection." (PMID 32843067, 2020). "In support of our findings, an increase in cytokines related to the inflammatory environment in placental ZIKV infection has already been observed in another study performed by our group, with an increase in TNF-α and the VEGFR-2 receptor." (PMID 32316163, 2020). "We also investigated differential secretion of inflammatory cytokines, such as TNF-α, following ZIKV infection as a possible mechanism of ZIKV-induced cell death." (PMID 33207682, 2020). "TNF-α upregulation, microgliosis and upregulation of complement system proteins, C1q and C3, are induced by ZIKV infection." (PMID 31488835, 2019). "No variation in the percentage of cells engaged in early apoptosis (BAX+) 8 h after the onset of treatment was observed when TNFα/CHX was added 2 h prior to ZIKV infection." (PMID 31671831, 2019).
ZIKV infection (continued). "DEG assays and pathway analysis showed that ZIKV infection triggered strong activation of the TNF signaling pathway and upregulated the expression of several cytokines, including IP-10 (CXCL10)." (PMID 30228241, 2018). "The effect of CD14+ monocyte depletion was observed in the levels of stem cell factor (SCF) and tumor necrosis factor alpha (TNF-α) only after ZIKV infection." (PMID 29600283, 2018). "Our data show that in the 3-D model of microvascular endothelial cells that we describe, TNF-α exposure significantly enhanced ZIKV infection of the endothelium itself." (PMID 28656176, 2017). "Here, we observe ZIKV infection to elevate secretion of the principal triad of pro-inflammatory cytokines (IL-1, IL-6, and TNF-alpha) by both brain tumour cell lines, in addition to many other cytokines that we report for the first time to be a component of oZIKV infection." (PMID 40240536, 2025). "This could be due to the release of inflammatory cytokines such as TNFα induced by ZIKV infection into the amniotic fluid, which came into extensive contact with perinatal fetal tissues in the uterus, causing inflammation and damage to these sites." (PMID 39998269, 2025). "As a pleiotropic molecule, IFN acts synergistically with TNF-α and IL-10, indicating that the tissue’s response to ZIKV infection involves not only attempts to control viral replication but also the recruitment and activation of diverse immune cells at the infection site." (PMID 41474758, 2025). "Thus, we show that ZIKV infection of brain tumour cells leads to the upregulated expression and secretion of key members of both TNF alpha and TNFSF9/TNFRSF9 signalling pathways." (PMID 40240536, 2025). "It was determined that Zika virus infection triggers the tumor necrosis factor (TNF) signaling pathway, which suggests that ZIKV-LAV treatment may not only cause direct cell death but also activate antitumor immunity." (PMID 37896752, 2023). "While we previously confirmed that Tnfa was induced at the transcriptional level in the brain in vivo following ZIKV infection, we next wanted to confirm that a robust TNF-α-dependent signature could indeed be observed following infection." (PMID 35462541, 2022). "Thus, it would be interesting to further explore the role of EGR1 in regulating PTGS2 and TNF-α expression following ZIKV infection." (PMID 35746681, 2022). "In addition, ZIKV infection increases the amounts of neurotoxic cytokines, i.e., TNF and IL-1β, in neuronal cultures and blockade of these factors suppresses neuronal cell death." (PMID 33658344, 2021). "Interestingly, the TNF-α secretion level also increased in a time-dependent manner following ZIKV infection." (PMID 33207682, 2020). "Indeed, it has been demonstrated that ZIKV infection is capable of triggering the production of proinflammatory cytokines, such as TNF and IL-β, and glutamate, mediators shown to induce neuronal cell death in ZIKV." (PMID 33251156, 2020). "Infection of both WNV and ZIKV in IL-22-/- mice led to alleviated clinical manifestations with decreased viral load and elevated pro-inflammatory TNF-α expression in the brain, whereas rIL-22 cytokine treatment in vivo played a detrimental role in ZIKV infection." (PMID 32843067, 2020). "We do not know whether lower levels of IL-1β, IL-6, IL-8, IL-10, IL-12, IL-13, IL-17A, TNF, and IFN-γ in ZIKV offspring at 32 days were caused by subclinical in utero ZIKV infection or maternal cytokine background." (PMID 31725819, 2019). "The results obtained in the present study indicate that ZIKV infection induces neuroinflammation in microglia which leads to the production of IL-6, TNF-α, IL-1β and IFNs, molecules with strong pro-inflammatory effects that feature among the most potent neuroinflammatory cytokines." (PMID 30359409, 2018). "Importantly, ZIKV infection increased IL-1β and TNF-α expression levels and blockade of these cytokines decreased Ca2+ influx and neuronal cell death." (PMID 28878777, 2017).
ZIKV infection (continued). "Next, we determined whether proinflammatory cytokines known to disrupt junctional complexes, such as TNF-α, and which are produced during flavivirus infections, enhanced the susceptibility of 3-D cells to DENV and ZIKV infection." (PMID 28656176, 2017). "Furthermore, ZIKV infection inhibited drug-induced cell death in both iBMDMs and BMDMs, specifically in response to treatments with lipopolysaccharide (LPS) combined with nigericin (Ni) or with tumor necrosis factor (TNF) combined with cycloheximide (CHX)." (PMID 39976465, 2025). "Indeed, ZIKV infection in immunized organoids leads to microglial activation and the subsequent induction of proinflammatory cytokines such as IL-6, IL-1β, and tumor necrosis factor (TNF), thus linking microglia with ZIKV-induced neuropathology." (PMID 38997413, 2024). "We demonstrated that ZIKV infection could induce placental pyroptosis through the recognition of the viral genome by RIG-I followed by TNF-α release, which activates the caspase-8- and caspase-3-mediated cleavage of pyroptosis executor GSDME in placental cells." (PMID 35972780, 2022). "Conversely, a previous report showed that ZIKV infection in murine neuronal cells leads to neurotoxicity and death and that TNF-α release plays an important role in this process, suggesting that inflammatory mechanisms triggered by ZIKV infection may differ across different experimental conditions." (PMID 34834918, 2021). "Moreover, ZIKV-activated microglia may also facilitate astrocyte activation through the production of TNF-α and IL-1β, which were highly expressed in the brain following ZIKV infection." (PMID 32843067, 2020). "ZIKV infection triggered the upregulation of multiple cytokines in humans during acute phase of infection that we were able to characterize by Luminex assay, including IP-10, IL-5, GM-CSF, TNF-α, IL-15, IL-10, MIP-1α, IFN-γ, IL-6, IL-1RA, IL-2, MIG, IFN-α, IL-2R, and IL-4." (PMID 30333476, 2018). "To evaluate the impact of ZIKV infection on macrophage cell death, we infected iBMDMs with ZIKV or treated them with LPS plus Ni or TNF plus CHX." (PMID 39976465, 2025). "During ZIKV infection, MEL reduces expression of TNFα, MX1 and IFI44L but significantly increases expression of IL-1β and IFNβ." (PMID 40821819, 2025). "Given the importance of T cell responses in controlling ZIKV infection, we measured the ability of ZIKV specific T cell populations from immunized mice to secrete IFN‐γ, TNF‐α, and IL‐2 in response to ZIKV E protein stimulation." (PMID 39010673, 2024). "In summary, ZIKV infection of the brain induced the expression of proinflammatory cytokines, including IL-1β, IL-6, IFN-γ, and TNF-α, in Ifnar1−/− mice." (PMID 37191498, 2023). "Effector CD8+ T-cells are also found to produce IFN-γ and TNF-α, and CD8+ levels are increased in ZIKV infection, accompanied with increased expression of granzyme B on them." (PMID 34745123, 2021). "It has been reported that some genes, such as TNF, NOS2, PTGS2, and VEGFA, as well as their proteins, are overexpressed during ZIKV infection, acting on the inflammatory response mechanism." (PMID 33672623, 2021). "CD4+ T cells were found to differentiate into Th1 cells during ZIKV infection as evidenced by the increased production of IFN-γ, IL-2 and TNF-α cytokines and transcription factor T-bet." (PMID 34745123, 2021). "We found that, similar to ZIKV infection, ZIKV C6/36 EVs were able to induce TNF-α mRNA expression in endothelial vascular cells." (PMID 31947958, 2020). "We found that, like ZIKV infection, the ZIKV C6/36 EVs were able to induce TNF-α mRNA expression in endothelial vascular cells." (PMID 31947958, 2020). "Even both of them induced apparent liver inflammation, ZIKV infection showed a more severe inflammatory response than DENV-2 infection based on the inflammation scores and the gene expression levels of IL-1β, TNF, IL-6, and TGFβ-2 in liver." (PMID 31191474, 2019).